TLR4 (toll like receptor 4)
Diseases named in the same sentence as TLR4 in open-access papers (continued):
Sharing a sentence is not in itself a finding about the gene and the disease.
melanoma (continued). "In murine macrophages, PTX-mediated stimulation of TLR4 not only induced the acquisition of an M1 phenotype, as indicated by the secretion of TNFα and IL-12 but was also able to counteract M2 polarization and to revert melanoma TAMs towards an M1 profile, which in turn caused melanoma regression." (PMID 34712615, 2021). "In addition, TLR4 is associated with induction of proliferation and migration of melanoma cells." (PMID 33980826, 2021). "But the functions of the mutated TLR4 in melanoma are still unknown." (PMID 32312954, 2020). "Simultaneously, a 1.69-fold amplification of the number of macrophages exists in the BAL fluid stemmed from wild-type mice bearing melanoma when compared with that from tumor-bearing TLR4-deficient mice, the result suggested that TLR4 may play a role in macrophage migration." (PMID 29029545, 2017). "TLR-4 promotes melanoma cell growth and survival and is essential for inducing tumor resistance to paclitaxel (PTX)." (PMID 40404908, 2025). "Together, these findings demonstrate that CCRL2 governs transcriptional programs in melanoma cells through bidirectional modulation of TLR4 and IFNAR signaling pathways." (PMID 40867595, 2025). "HMGB1 can serve as a ligand for TLR4 in melanoma, is highly expressed in tumors, and drives MDSC activity upon activation." (PMID 40727252, 2025). "Building on this, a hexavalent melanoma vaccine encapsulated in immunogenic nanoliposomes with TLR4 agonist KDO2 demonstrated enhanced CD8+/CD4+ T cell priming." (PMID 40861441, 2025). "During melanoma progression, recruitment and transformation of neutrophils into a proangiogenic state through TLR4 activation facilitate lung metastasis." (PMID 40727252, 2025). "Toll-like receptor 4 (TLR4) expression has been observed in 90% of human primary melanoma lesions and 93% of metastatic lesions." (PMID 39723372, 2024). "BHS also potentiated paclitaxel chemotherapy in human melanoma by inducing apoptosis via inhibiting the TLR4 pathway." (PMID 39051750, 2024). "Research on TLR4 has been conducted in skin and cervical cancer using B16-F10 melanoma and HeLa adenocarcinoma cell lines, respectively." (PMID 39640496, 2024). "The TLR4 D299G and T399I variants were associated with nodal metastasis, advanced stage III, and severity of melanoma." (PMID 38606218, 2024). "DAMPs in TRIMEL increase DC surface marker expression, cytokine gene expression, and the capacity to activate melanoma-specific TILs via TLR4." (PMID 38675738, 2024). "The experimental evidence has shown significantly higher expression of TLR4 in B16-F10 melanoma cells compared to normal skin cells and also demonstrate an increase in TLR4 expression in LPS-stimulated HeLa cells." (PMID 39640496, 2024). "An upregulation of TLR4 expression detected in the melanoma A375 cell lysate served as a control for effective LPS stimulation and cellular responsiveness." (PMID 39451259, 2024). "TLR4 is also targeted by tumor suppressor miRNAs like miR-216a in renal cell carcinoma, miR-145-5p in melanoma and miR-122 in hepatocellular carcinoma, paralleling the miR-5195-3p/TLR4 axis in CRC." (PMID 39390599, 2024). "As a ligand for TLR4, LPS promotes the proliferation and migration of TLR4-positive melanoma cells through signal transduction mediated by transcriptional activator 3 (STAT3) activation." (PMID 39723372, 2024). "BGs are attractive targets for phagocytosis by melanoma cells primarily because of the membrane LPS that activates TLR-4 (constitutively expressed in melanoma cells) enhancing the production of IL-8 and cell adhesion." (PMID 39340000, 2024). "Tumour-derived inflammatory glycoprotein PTX3 promotes melanoma cell invasion through a TLR4-dependent pathway." (PMID 38052785, 2023). "Small fragments of the extracellular matrix component HA (sHA) also enhance the motility of cancer cells through the TLR4 signaling pathway in melanoma and papillary thyroid carcinoma." (PMID 36982351, 2023).
melanoma (continued). "It was suggested that activation of PPARƴ inhibited the proliferation of melanoma cells and induced apoptosis via inhibiting the Toll-like receptor-4 (TLR-4)-dependent NF-κB pathway." (PMID 36834531, 2023). "In an in vivo melanoma model, ultraviolet (UV) irradiation induced a TLR4/MYD88-driven neutrophilic skin inflammatory response initiated by high mobility group box 1 (HMGB1) release from ultraviolet-damaged keratinocytes." (PMID 37525065, 2023). "Tea polyphenols inhibited the proliferation, migration, and invasion of melanoma cells in a dose and time-dependent manner through the downregulation of toll-like receptor 4 (TLR4)." (PMID 36829966, 2023). "proved that extracellular HMGB1 is an essential factor for TLR4 interaction with platelets and promotes melanoma tumor cells’ interaction with aggregation, extravasation, and metastasis." (PMID 37168380, 2023). "S100A4 can also bind to TLR4 on MDSCs in fibrosarcoma-, melanoma-, and lung cancer-bearing mouse models." (PMID 36911674, 2023). "In a study, it was found that nuciferine exhibited inhibitory properties on the p65 signaling pathway in melanoma cells by specifically targeting Toll-like receptor 4 (TLR4)." (PMID 37833979, 2023). "MiR-145-5p, a TLR4-expression antagonist that inhibits carcinogenesis and metastasis via the NF-κB signaling pathway, is downregulated in tumor tissue of patients with melanoma." (PMID 36012593, 2022). "Given the role of Peli1 in other tumors and that of TLR4/NF-κB in melanomas, this study examined the effect of Peli1 and the related signaling pathways that influence the occurrence and development of melanomas." (PMID 36422271, 2022). "To examine the role of TLR4 in PA-induced proliferation and invasion in melanoma cells, we inhibited the functional activity of TLR4 using a TLR4 selective antagonist (TAK-242)." (PMID 36422271, 2022). "Higher levels of TLR4 have already been correlated with high PD-L1 in non-small cell lung cancer, melanoma, and T-cell lymphomas." (PMID 35327577, 2022). "A DC-based mRNA vaccine encoding CD40Ligand, CD70, and TLR4 (TriMixDC), and transfected with melanoma associated genes (MAGE, Tyrosinase, gp100-TriMix-MEL) was evaluated in a cohort of advanced melanoma patients." (PMID 36016150, 2022). "Cancer cell-derived long pentraxin 3 promoted melanoma migration through TLR4/NF-κB signalling pathway." (PMID 35280672, 2022). "According to our previous study, sCRT promoted the malignant progression of murine melanoma mainly through TLR4- and S100A8/9-mediated MDSC differentiation/generation and recruitment." (PMID 36249426, 2022). "GEVs induced macrophage polarization to the M1 phenotype via vesicular ceramides (Cers) and Toll-like receptor 4 on macrophages, thereby inhibiting melanoma growth." (PMID 33668388, 2021). "Recent data presented by the Rathore group suggest its role in the promotion of migration of melanoma cells through the TLR4/NF-κB signalling pathway." (PMID 34283046, 2021). "This biological role for TLR4 in melanoma is partially in contrast with our observation of a better survival in melanoma patients with higher TLR4 levels." (PMID 33980826, 2021). "This miRNA was downregulated in melanoma tissues and cells and suppressed TLR4 expression by binding to its 3’-UTR in melanoma cells." (PMID 34149728, 2021). "Specifically, LPS-induced STAT3-signaling, as a result of TLR4 activation, elevates B16-F10 melanoma growth, angiogenesis, and invasion in vitro and in vivo." (PMID 33922465, 2021). "Cancer cell-derived long pentraxin 3 enhances melanoma migration and invasion through TLR4/NF-κB signaling pathway." (PMID 34552063, 2021). "B16 melanoma cells that express MMP2 at baseline have slower kinetics in Tlr2–/–Tlr4–/– mice, implicating MMP2 in promoting tumor growth." (PMID 34032639, 2021). "For example, it was recently found that melanoma-derived EVs can stimulate PD-L1 expression in myeloid cells via TLR4 signaling." (PMID 34829995, 2021).
melanoma (continued). "When we assessed the association of TLR4, ITGA6, and BTG2 gene expression with melanoma prognosis, we observed that their higher expression (median cutoff) was significantly associated with a worse overall survival in TCGA SKCM cohort of 458 samples." (PMID 33980826, 2021). "Overall, this study demonstrates that activation of STAT3 is a critical event in TLR4 signaling-mediated melanoma progression." (PMID 32312954, 2020). "Among all family members, TLR-4 is expressed in 90% of primary and 93% of metastatic melanomas, where it plays a role in the aggressive behavior of cancer cells." (PMID 33193402, 2020). "Paclitaxel induced TAMs toward an M1-like profile in mouse models of melanoma and breast tumors which was depended on the presence of Toll-Like receptor 4 (TLR4) on myeloid cells." (PMID 32656079, 2020). "EMT-like morphological features, such as losing cell-cell interaction and a spindle-shaped phenotype, were observed in A375CA-TLR4 cells, suggesting that TLR4 activation promotes EMT in melanoma." (PMID 32312954, 2020). "Notwithstanding, these results show that TLR4 signaling in melanoma cells increases the secretion of immunosuppressive cytokines that can be upregulated by STAT3." (PMID 32312954, 2020). "In this study, we established TLR4/MYD88/STAT3 and TLR4/TRIF/STAT3 pathways in melanoma and demonstrated their pathogenic roles." (PMID 32312954, 2020). "We also found that activation of STAT3 is a key event in TLR4 signaling-mediated melanoma development." (PMID 32312954, 2020). "We have shown for the first time that pioglitazone reduced melanoma progression by suppressing TLR4 signaling pathway and inflammatory cytokines." (PMID 32665906, 2020). "The results of IHC staining imply an important role of STAT3 activation in TLR4 signaling-mediated melanoma growth, angiogenesis and EMT." (PMID 32312954, 2020). "In melanoma, neutrophils recruited by Toll-like receptor 4 (TLR4) signal can induce cancer cells to migrate to endothelial cells through tumor necrosis factor (TNF), resulting in enhancing cancer metastasis." (PMID 33488618, 2020). "Collectively, our work identifies STAT3 activation as a key event in TLR4 signaling-mediated melanoma progression, shedding new light on the pathophysiology of melanoma." (PMID 32312954, 2020). "During melanomagenesis, ultraviolet radiation recruits and activates neutrophils in a TLR4-mediated mechanism, inducing an inflammation that facilitates angiogenesis and favors melanoma angiotropism." (PMID 33193402, 2020). "Third, we found that constitutive TLR4 signaling enhances STAT3 activation in melanoma tissues and promotes tumor growth, angiogenesis and epithelial–mesenchymal transition (EMT) in mice." (PMID 32312954, 2020). "Further research in in vivo models of melanoma is needed to better understand of interaction between PPARγ and TLR4 signaling in this cancer." (PMID 32665906, 2020). "In the present study, we found that protein levels of TLR4 were significantly elevated in melanoma tissues compared to that in normal tissues." (PMID 32312954, 2020). "Activation of TLR4 can inhibit melanoma cell death while TLR4 inhibition led to inhibition of their survival." (PMID 32665906, 2020). "Together, these data indicate that activation of TLR4 enhances STAT3 activation in melanoma tissues and promotes tumor growth, angiogenesis and EMT in mice." (PMID 32312954, 2020). "In this study, our findings provide evidence that STAT3 is a key player in TLR4 signaling-mediated melanoma progression." (PMID 32312954, 2020). "The changes of immune cell profiles imply that activation of STAT3 contributes to TLR4 signaling-mediated immunosuppression in melanoma microenvironment." (PMID 32312954, 2020). "We further found that LPS promoted tumor growth and STAT3 activation in B16NC tumors, but had less effect in B16STAT3β tumors, indicating that STAT3 activation plays a positive role in TLR4 signaling-mediated melanoma growth." (PMID 32312954, 2020).
melanoma (continued). "TLR-4 signaling involves the activation of signal transducer and activator of transcription 3 (STAT3), which on turn promotes melanoma growth and aggressiveness associated features including angiogenesis and epithelial to mesenchymal transition." (PMID 33193402, 2020). "Our findings suggest that caution should be taken when using MPLAs or other TLR4/TRIF pathway activators to treat melanoma." (PMID 32312954, 2020). "Clinically, we find that high levels of TRIM44 combined with upregulation of TLR4 serves as a promising prognostic indicator in melanoma patients." (PMID 30922374, 2019). "TRIM44, regulated by miR-26b-5p, promotes melanoma progression by stabilizing TLR4, which then activates the AKT/mTOR pathway." (PMID 30922374, 2019). "TLR4 expression has been reported in several cancers, including human head and neck cancer, human laryngeal and oral cancer cell line and melanoma." (PMID 31318878, 2019). "This suggests that overexpression of TRIM44 and TLR4 are indicators of a poor prognosis in melanoma patients." (PMID 30922374, 2019). "To further explore the relationship between TRIM44 and TLR4, we quantified TRIM44 and TLR4 expression in 20 melanoma tissue samples." (PMID 30922374, 2019). "In contrast, there is also a significant reduction in TLR-4 expression in melanoma-bearing mice, indicating a strong suppressor effect of melanoma on its level." (PMID 29588627, 2018). "Melanoma growth was associated with a significant reduction in TNF-α, TLR-2 and TLR-4 mRNA expression in peritoneal macrophages compared to that in control mice (P < 0.05)." (PMID 29588627, 2018). "Taken all together, it suggests that PTX can induce drug resistance in MDA-MB-231 BCA and MDA-MB-435 melanoma cells via a TLR4 dependent pathway." (PMID 29486738, 2018). "TNF-α mRNA expression in melanoma-bearing mice (M) was reduced by 83% compared to control mice while TLR-4 and TLR-2 mRNA expression was suppressed by 70% and 35%, respectively compared to control mice." (PMID 29588627, 2018). "The effect of tea polyphenols on Toll-like receptor 4 (TLR4) in melanoma cell lines has been reported recently." (PMID 30585192, 2018). "Toll-like receptor 4 (TLR4) had been reported toplay an important role in melanoma, and tea polyphenol (TP) is regarded as ananticancer substance." (PMID 29359608, 2018). "The inhibition of TLR4 in melanoma cell lines inhibited cell proliferation, migration, and invasion, and blocking the expression of 67LR eliminated the effects of tea polyphenols on TLR4." (PMID 30585192, 2018). "Treatment with tea polyphenols inhibited TLR4 expression both in normal melanomas and in stimulated melanomas by TLR4 agonist lipopolysaccharides." (PMID 30585192, 2018). "Not only was TLR-4 secreted in considerable amounts in human melanomas, but it was shown to be important for cancer cell growth and migration." (PMID 26395996, 2016). "Our results show that BLS acts directly in cultured tumor cells via TLR4, highly suggesting that BLS elicits its therapeutic effects acting on the TLR4 from B16 melanoma cells." (PMID 25973756, 2015). "As regarding tumor cells, exposure of human melanoma cells to HA fragments leads, via TLR4, to NF-κB activation followed by enhanced expression of matrix metalloprotease (MMP) 2 and interleukin (IL)-8, factors that can contribute to melanoma progression." (PMID 25926834, 2015). "We can conclude that the direct effect induced by BLS in B16 melanoma is dependent on tumor TLR4 as this effect disappears when this receptor is blocked with a monoclonal antibody before stimulation." (PMID 25973756, 2015). "In human melanoma A375 cells, the inhibition of TLR4/MyD88 signaling effectively decreased both VEGF and IL-8 levels with paclitaxel and icariside II combination treatment." (PMID 24744758, 2014). "The over-expression of TLR4 within melanoma tumors triggers an inflammatory response leading to tumor development." (PMID 24744758, 2014).
melanoma (continued). "Small HA fragments have also been shown to enhance migration of melanoma cells in a TLR-4-dependent manner, and larger HA oligosaccharides induce the maturation of dendritic cells via TLR-4." (PMID 24213471, 2012). "TLR4 is associated with metastasis also in other types of cancer, such as melanoma, where TLR4 activation induces cell migration, and prostate cancer." (PMID 22110526, 2011). "Distribution of the most common haplotypes within TLR2, TLR3 and TLR4 in German melanoma patients and German controls." (PMID 21931695, 2011). "Our results now clearly demonstrate that the autophagy-associated cell death is involved in the mechanism by which the prophylactic application of the TLR4/9 agonist complex promotes B16 melanoma cell apoptosis." (PMID 21931823, 2011). "In particular, melanoma cells are reported to express TLR-4, respond to lipopolysaccharide (LPS) and produce interleukin (IL)-8." (PMID 17156435, 2006). "Notably, intratumoral administration of the conjugated TLR4/TLR7 ligand resulted in significant antitumor activity in a syngeneic B16F10 melanoma model." (PMID 42087448, 2026). "Similarly, autophagosomes secreted by melanoma cells stimulate p38-STAT3 signaling in macrophages through TLR4, thus promoting macrophages M2 polarization to inhibit CD8 + T cell antitumor functions." (PMID 40908470, 2025). "Similarly, ginseng-derived extracellular vesicles (GDNPs) polarized M2-TAMs to pro-inflammatory M1 phenotypes via TLR4/MyD88 signaling, inducing ROS-mediated apoptosis in melanoma cells and synergizing with ACT." (PMID 40861441, 2025). "BHS also potentiated paclitaxel‐induced apoptosis in human melanoma by inhibiting TLR4 signalling." (PMID 39051750, 2024). "For instance, in a murine model of transplanted melanoma, prophylactic application of TLR4/9 agonists (before tumor inoculation) can activate the IFNγ/STAT1 signaling pathway, promoting tumor cell autophagy and autophagy-related tumor cell death, subsequently reducing metastasis." (PMID 38523155, 2024). "When being internalized by TAM, GDNPs could promote M1-like polarization via TLR-4/MyD88 signaling pathway and increase the production of total ROS, which then induced the apoptosis of mouse melanoma cells and inhibited tumor growth in vivo." (PMID 37575250, 2023). "Additionally, the anti-inflammatory activity of fenofibrate was enhanced by the inhibition of the TLR-4 signaling pathway in melanoma." (PMID 36834531, 2023). "However, when melanoma-derived EVs were added to TLR4-knockout IMCs, the upregulation of PD-L1 was blocked." (PMID 36911674, 2023). "JNK contributes to immune evasion via PD-L1 expression by modulating the activity of c-Jun, an inducible transcription factor that directs gene expression changes such as PD-L1, a mechanism observed in melanoma; or via TLR4 (toll-like receptor 4) signaling as in bladder cancer." (PMID 38299143, 2023). "Moreover, HSP90α converts monocytes to immunosuppressive myeloid cells in melanoma through TLR4 signaling." (PMID 36982351, 2023). "Its role in mediating the TLR4/TRIF-Peli1-pNF-κB axis pathway may provide a new idea for the treatment of melanomas." (PMID 36422271, 2022). "TLR4/NF-κB can promote the proliferation and invasion of melanomas." (PMID 36422271, 2022). "However, in the present study, we indicated that TLR4 was a ligand of PA, which promoted the lung metastasis of melanomas by activating TLR4 as well as the nuclear translocation of pNF-κB, influencing the translation of E-cadherin, MMP2, and Vimentin." (PMID 36422271, 2022). "After silencing TLR4, the cell migration ability of melanomas was decreased." (PMID 36422271, 2022). "Therefore, we concluded that palmitic acid promoted the lung metastasis of melanomas through the TLR4/TRIF-Peli1-pNF-κB pathway." (PMID 36422271, 2022). "TLR4 activates NF-κB to promote the occurrence and development of melanomas." (PMID 36422271, 2022).